MSTN (myostatin)
Diseases named in the same sentence as MSTN in open-access papers (continued):
Sharing a sentence is not in itself a finding about the gene and the disease.
cancer (continued). "Unfortunately, the occurrence, development, and changes of MSTN in the process of cancer have not been fully revealed." (PMID 30922397, 2019). "Cisplatin was also show to up-regulate the expression of myostatin, a member of the TGF-beta family of growth factors also known to negatively regulate muscle mass in the occurrence of cancer, thus contributing to muscle wasting via activation of proteasome-dependent muscle catabolism." (PMID 27259276, 2016). "According to our results, the particular cancer patients we examined did not suffer from tumors with myostatin dependent cachexia." (PMID 24260393, 2013). "Preclinical studies with anti-MSTN treatments (anti-MSTN antibodies, MSTN propeptide with inhibitory function, inhibitors of the MSTN receptor, activin-receptor IIB) have been conducted, providing encouraging results in the field of skeletal muscular dystrophy, aging and cancer-related cachexia." (PMID 35806921, 2022). "Currently, myostatin inhibition has not been applied to clinical therapy of cancer cachexia." (PMID 30922397, 2019). "Finally, we found drugs targeting MSTN, CXCL12, and CAMK2B, which may be considered for the development of novel therapeutic strategies for cancer cachexia." (PMID 31013615, 2019). "Indeed, several indications recommended the use of strategies aimed at antagonizing myostatin in order to enhance muscle anabolism and prevent muscle catabolism in cancer cachexia and to prolong life, even in the absence of direct effects on tumor growth." (PMID 27259276, 2016). "They conclude that muscle depletion in cancer cachexia might depend upon myostatin and related ligands rather than on pro-inflammatory cytokines alone." (PMID 21799891, 2011). "Interestingly, the myostatin pathway might not be the only pathway involved in cancer cachexia." (PMID 31285507, 2019). "By interacting with a disintegrin and metalloproteinase 12 (ADAM12), transforming growth factor-β ligands (activin, myostatin and growth differentiation factor (GDF) 11), FSTL3 can either activate or inhibit these molecules in human non-tumor pathophysiologies and cancers." (PMID 36325361, 2022).
tumor (65 papers, 2009 to 2026). "In fact, experimental blockade of myostatin/activin (such as with ACVR2B receptors traps) in tumor-bearing mice not only increases muscle mass but also prevents cachexia-associated bone loss, reinforcing the myostatin link in muscle–bone pathology." (PMID 40869331, 2025). "Chemotherapy, as one of the main modalities of antitumor therapy, has an active and effective antitumor effect that can fundamentally reverse the uncontrollable myostatin breakdown caused by tumor growth." (PMID 36523983, 2022). "In animal models and human muscle biopsies, some evidence indicates that myostatin levels and myostatin-associated signaling are activated as a result of the tumor burden." (PMID 36078078, 2022). "Myostatin inhibitor treatment in our krasG12V fish also significantly alleviated tumor-induced loss of body weight and muscle fibers." (PMID 30718259, 2019). "Consistently, ERK activation is associated with myostatin upregulation both in the muscle of tumor-bearing animals and in TNFα-treated C2C12 myotubes, suggesting the possibility of a causal relationship between the two events." (PMID 21048967, 2010). "Taken together, the data suggest that the loss of adipose tissue in mice with high serum myostatin caused by a myostatin-secreting tumor required supraphysiologic levels of myostatin." (PMID 19295913, 2009). "Prostaglandin E2 and pro-inflammatory cytokines such as interleukins (IL-1, IL-6), tumor necrosis factor (TNF), interferon, TNF receptor-associated factor 6, and other tumor-derived catabolic factors like activin and myostatin (MSTN) are examples of such mediators." (PMID 35565236, 2022). "In addition, high tumoral myostatin levels were associated with greater infiltration of tumor-associated macrophages and worse survival, suggesting that tumor-produced myostatin can have both systemic (muscle-wasting) and local (tumor microenvironment) effects." (PMID 40869331, 2025). "Additionally, MSTN inhibitors could generate potential side effects, including the increased risk of tumor development; thus, further research is necessary to evaluate the safety issue." (PMID 37892843, 2023). "Moreover, DNA methylation plays a regulatory role for BDNF and MSTN, lower methylation levels may cause an abnormal increase of BDNF and MSTN in tumor samples." (PMID 36733390, 2022). "C26-tumor-bearing mice were treated with a soluble receptor of the ActRIIB (sActRIIB), which improved survival and muscle mass without reducing tumor size and by treating the Lewis lung cancer-model with myostatin antibodies, muscular atrophy and loss of muscle force were attenuated." (PMID 33802348, 2021). "In animal models, the LJFE‐E‐injected C26 tumor‐bearing group showed lower transcript‐level expression of MSTN, MuRF1, and MAFbx32 in the gastrocnemius muscles than the C26 tumor‐bearing group." (PMID 40672545, 2025). "Aerobic exercise, on the other hand, can regulate the tumor environment by secreting muscle factors such as irisin and myostatin, and can also improve metabolic capacity by modulating the activity of lactate metabolic enzymes, including LDH." (PMID 40704062, 2025). "Repeated administration of RBC-EVs containing siRNA against myostatin resulted in >80% myostatin reduction in skeletal muscle, which produced larger muscle fibers and blocked cachexia development in tumor-bearing mice." (PMID 40869331, 2025). "Of all the remaining myokines, tumor tissues showed higher expression only for IL-15 and myostatin with relative abundance ratios of 2.4 and 3.1, respectively." (PMID 39411315, 2024). "Relative tissue myokine expression evaluated by the LC-MS/MS method showed increased tumor levels only for IL-15 and myostatin, arguing against the possibility of increased production of cachexia related mediators within the tumor." (PMID 39411315, 2024). "Among these, myostatin is associated with transforming growth factor-β, interleukin-15, NK cells, CD3, and CD8 T cells, all of which are linked to tumor progression." (PMID 38890682, 2024).
tumor (continued). "Of all the evaluated myokines, tumour tissues showed higher expression levels only for IL-15 and myostatin." (PMID 39411315, 2024). "We found that four muscle failure-related genes (BDNF, FNDC5, IL15, MSTN) were significantly increased in tumor cells." (PMID 36733390, 2022). "The mRNA expression of BDNF, IL15, and MSTN were significantly higher in tumor tissues than in paraneoplastic tissues, while the expression of FNDC5 was significantly reduced in tumor tissues." (PMID 36733390, 2022). "Then, we examined the mRNA expression levels of BDNF, FNDC5, IL15, and MSTN, in tumor tissues and paracancerous tissues." (PMID 36733390, 2022). "We examined the mRNA expression of four myokine/exerkine genes, BDNF, FNDC5, IL15, and MSTN, in tumor and paraneoplastic tissues." (PMID 36733390, 2022). "SIRT6 over‐expression significantly reduced myostatin expression and plasma free fatty acids levels but maintained plasma insulin levels in tumour‐bearing mice." (PMID 34212132, 2021). "It is well known that counteraction of the ACVR2B receptor disrupts the signalling mediated by several TGF‐β superfamily members and potently corrects the levels of myostatin, a negative regulator of muscle mass, within skeletal muscle in tumour‐bearing mice." (PMID 33200567, 2020). "This novel finding sets the ground for further research on the role of myostatin in uterine pain perception and indicates the necessity of investigating the impact of myostatin expression in various neoplasms on the circulating myostatin level." (PMID 32796600, 2020). "It has been also shown that inactivation of the myostatin gene decreases tumor growth in myostatin-knockout animal models." (PMID 33198216, 2020). "Activin and myostatin, other catabolic factors driven by the tumor, have also been described as mediators of metabolic derangement." (PMID 32230855, 2020). "Activin/myostatin signaling has a critical role not only in cachexia but also in tumor angiogenesis." (PMID 32970737, 2020). "Based on staining for PCNA+ hepatocytes, we found a significant promotion of tumor cell proliferation by myostatin inhibition." (PMID 30718259, 2019). "In previous studies, treatment with CT-26 CM suppressed myoblast proliferation and differentiation into myotubes and accelerated myotube degradation, suggesting that tumor-derived factors such as myostatin and IL-6 promote skeletal muscle wasting." (PMID 29662645, 2018). "Skeletal muscle wasting involves the production of pro-inflammatory cytokines derived from tumor and immune cells, and negative regulation of insulin-like growth factor-1 signaling by myostatin and activin." (PMID 29630652, 2018). "Several molecular signaling pathways within the myocyte have been implicated in driving tumor-induced muscle wasting, including forkhead boxO (FoxO), signal transducer and activator of transcription 3 (STAT3), and myostatin-activin receptor 2B." (PMID 27901481, 2017). "Mice with 4T1 OCIB also had higher relative mRNA expression of myostatin, a strong negative regulator of skeletal muscle mass, compared to non-tumor controls." (PMID 29312148, 2017). "Some reports have shown that myostatin signalling is enhanced in the skeletal muscle of tumour-bearing rats and mice." (PMID 26508818, 2015). "In this report, we demonstrated that tumor-induced myostatin in turn induced TNF-α, thus activating calcium-dependent and proteasomal protein degradation." (PMID 25797259, 2015). "The reduction of myostatin in muscle is likely through inhibiting humoral mediator(s) secreted by the implanted tumor cells or host cells in response to chemotherapy." (PMID 25797259, 2015). "The IL-6 level significantly increased in tumor-bearing mice after chemotherapy, suggesting that both chemotherapeutic agent-induced IL-6 and myostatin promote muscle atrophy." (PMID 25797259, 2015).
tumor (continued). "In general, skeletal muscle atrophy results from overexpression of TNF-α and myostatin, which up-regulates calcium-activated and ubiquitin-proteasome systems in tumor mice." (PMID 25797259, 2015). "We found a slightly reduced abundance of myostatin prodomain in the serum of patients with tumor disease of the liver or the gastrointestinal tract and strong recent weight loss." (PMID 24260393, 2013). "Can tumor cells acquire myostatin expression during chemotherapy?" (PMID 40868997, 2025). "To further validate the efficacy of KIC, we evaluated myostatin expression in C2C12 myotubes exposed to tumour‐derived conditioned media (TCM) obtained from tumours excised from C26‐ and 4T1‐injected mice, thereby mimicking the cachectic tumour microenvironment in vitro." (PMID 40810552, 2025). "Moreover, tumour lysates from two independent mice from the xenograft assays showed that MHC levels were elevated and myostatin levels were significantly reduced in shBRD4-L tumours compared to shScr control and shBRD4-S tumours." (PMID 38191874, 2024). "The molecular mechanisms underlying the development of cancer cachexia remain poorly defined, although tumor-derived catabolic factors such as activins, myostatin, and pro-inflammatory cytokines arising from tumor-immune system crosstalk are thought to contribute to its progression." (PMID 37006254, 2023). "Besides its double-edged role as a tumor suppressor and activator, TGF-β causes muscle loss through myostatin-based signaling, involved in the reduction in protein synthesis and enhanced protein degradation." (PMID 36078078, 2022). "EE lowered circulating myostatin, IL-6 and slowed down tumour growth." (PMID 35008220, 2021). "Myostatin might be secreted from primary tumours, but its precise role in tumour metabolism remains unknown." (PMID 32478975, 2021). "MSTN blockade reduced the tumor expression of genes involved in angiogenesis (e.g. VEGF-A, HIF-1α)." (PMID 32970737, 2020). "Therefore, we investigated the effect of ajoene extract on the level of myokines such as IL-6 and myostatin in muscles of tumor-bearing mice." (PMID 31717643, 2019). "Similarly, mRNA expressions of IL-6R and myostatin were increased in the tumor control group, whereas they were significantly reduced in response to ajoene extract treatment (IL-6R, p = 0.042; myostatin, p < 0.001)." (PMID 31717643, 2019). "The effects of myostatin in tumor cachexia might depend on myostatin from skeletal muscle, but also on myostatin secreted from tumor cells." (PMID 24260393, 2013). "We found that in vivo moderate over‐expression of SIRT6 in skeletal muscle not only inhibited myostatin expression in autocrine manner but also normalized insulin levels and downregulated secretion of non‐esterified free‐fatty acid in the plasma via paracrine signalling in tumour‐bearing mice." (PMID 34212132, 2021). "Hence, we concluded that therapeutically targeting communication between tumor and muscle, such as inhibiting leptin signaling, could provide a more efficient treatment than targeting muscle or myostatin." (PMID 30718259, 2019). "Likewise, myostatin inhibition by the administration of an ActRIIB/Fragment-crystallizable (ActRIIB/Fc) fusion protein or the ActRIIB soluble form by antisense oligonucleotides is able to prevent the development of muscle mass depletion in tumour-bearing mice." (PMID 26508818, 2015). "Collectively, our data support a model where BRD4-L is involved in tumour progression and inhibits differentiation of ERMS cells, at least in part, by regulation of myostatin." (PMID 38191874, 2024). "The expression levels of BDNF, IL15, and MSTN were significantly higher in tumor tissues than in paraneoplastic tissues, while the expression level of FNDC5 was significantly reduced in tumor tissues." (PMID 36733390, 2022). "In C26 tumor-bearing BALB/c mice, involvement of myokines was further indicated as increased muscle IL-6, IL-6R, and myostatin expression accompanied muscle wasting in these mice." (PMID 33329046, 2020).
tumor (continued). "Myostatin and Smad3 phosphorylation were also similar in control, vehicle, and (+)-JQ1-treated muscles from C26-tumor-bearing mice." (PMID 29167426, 2017). "Taken together, the tumor-induced muscle atrophy is likely due to elevated levels of TNF-α and myostatin, which act together to activate NF-κB and FoxO1 so as to amplify the expressions of calpain (autolysis) and ubiquitin ligases (ubiquitin-proteasome)." (PMID 25797259, 2015). "The aim of the present review is to address the role of ghrelin, myostatin, leptin, HIF, IL-6, TNF-α, and ANGPTL-4 in the regulation of energy balance, tumour development, and tumoural cell invasion." (PMID 26508818, 2015). "In tumor-bearing mice under chemotherapy, supplementation with fish oil and selenium prevented a rise in IL-6, TNF-α and myostatin and muscle atrophy." (PMID 25797259, 2015). "Moreover, we confirmed via double staining that myostatin and desmin/SMA were expressed in the same tumor in an almost mutually exclusive pattern, even when myogenic markers were only focally expressed." (PMID 40868997, 2025). "It is also important to note that systemic myostatin administration has previously shown to induce fat wasting; hence, it is possible that ACVR2B/Fc administration prevents myostatin from acting directly on adipose tissue in the tumour‐bearing mice." (PMID 33200567, 2020). "At the cellular level, IMB0901 had no influence on anti-tumor effect of three chemotherapeutic agents (cisplatin, doxorubicin, and gemcitabine) and lowered doxorubicin-induced upregulation of MSTN in C2C12 myotubes." (PMID 30922397, 2019). "Our data are in agreement with previous reports showing that ghrelin administration prevented tumor and cisplatin-induced muscle wasting, through the down-regulation of inflammation of the p38/c/EBP-beta/myostatin axis and the activation of Akt, myogenin and myoD3." (PMID 29026190, 2017). "Myostatin and IL-6 significantly increase in the docetaxel-treated mice (TD), as opposed to that in tumor-bearing mice (T)." (PMID 25797259, 2015). "At present though, we cannot formally identify which ligand has potential tumour suppressor function since other TGF-β superfamily members can also activate canonical PO4-SMAD2 and 3 via their own distinct serine threonine receptor kinase complexes including Activin, Nodal, and GDF-8 (myostatin)." (PMID 29581863, 2018). "Furthermore, WCUP decreased the CT-26 cell-derived production of IL-6 and myostatin, by which WCUP-treated CT-26 CM showed less impairment of C2C12 myoblast proliferation and differentiation and prevention of tumor-induced C2C12 myotube wasting, compared with WCUP-untreated control CT-26 CM." (PMID 27064118, 2016). "LIF levels were markedly elevated in the C26 tumor milieu, whereas other known wasting factors (IL-6, TNF-α, myostatin) were not, indicating that LIF is the key wasting cytokine in this model." (PMID 40869331, 2025). "In KPC-injected cells mice, MCP1 increased notably and significantly during tumor growth while CRP and myostatin did not change significantly." (PMID 37629186, 2023). "We also observed that myostatin levels in plasma did not correlate with their RNA expression levels (MSTN RNA level measured by qPCR) in muscle after 1-MT treatment, especially in B16F10 tumor-bearing mice." (PMID 37629186, 2023).